CD4 (CD4 molecule)
Diseases named in the same sentence as CD4 in open-access papers (continued):
Sharing a sentence is not in itself a finding about the gene and the disease.
breast cancer (continued). "In this study, increased tumour grade and Ki-67 labelling index were associated with increased infiltration by CD68+ tumour-associated macrophages, CD4+ and CD8+ T lymphocytes and increased tumour microvessel density in patients with primary operable breast cancer." (PMID 18797461, 2008). "However, few studies have examined the association between tumour CD4+/CD8+ T-lymphocytic infiltration and/or CD68+ macrophage infiltration and survival in patients with primary operable breast cancer." (PMID 18797461, 2008). "Moreover, patients with metastatic HER2 + breast cancer and a good prognosis exhibited a higher proportion of CD4 + IL-2 + T cells relative to CD4 + IL-4 + T cells, along with an increased percentage of CD56bright NK cells, in their peripheral blood compared to patients with a poor prognosis." (PMID 41582199, 2026). "In addition to ADCP and ADCC, monocyte/macrophage cells may also secrete miR-19a-3p, thereby influencing its levels in breast cancer patients with a favorable prognosis, similar to CD4 + Th1 cells." (PMID 41582199, 2026). "In addition, prior studies have observed the expression level of MHC class II on the mammary tumor cells in tumor‐draining lymph nodes (TDLNs) was positively correlated with the progression of the metastasis in the LNs, by eliciting the CD4+ T cell tolerance and an immunosuppressive TME." (PMID 40400098, 2025). "Notably, we found that in our overall cohort of breast cancers, a positive correlation was found between pSTAT1 expression and the number of all analyzed immune cell populations (CD4+: Spearman r = 0.369, P < 0.001; CD20+: r = 0.326, P < 0.001; CD57+: Spearman r = 0.188, P < 0.001)." (PMID 38167507, 2024). "Therefore, we explored whether breast cancer cell exos-derived CCT2 regulated Ca2+ influx in CD4+ T cells." (PMID 39079960, 2024). "However, the underlying mechanism by which breast cancer cells stimulate CD4+ T cells activation has not been extensively elucidated." (PMID 39079960, 2024). "For example, in breast cancer, peritumoral immune cell infiltration is associated with cancer progression, whereas in pancreatic ductal adenocarcinoma (PDAC), intratumoral infiltration of immune cells such as CD3, CD4, and CD8 T cells is significantly correlated with better prognosis." (PMID 39273499, 2024). "Furthermore, we discovered that CCT2 can be encapsulated within exosomes and transferred from breast cancer cells to CD4+ T cells, where it suppresses CD4+ T cell activation by downregulating CD40L expression, thereby promoting tumor immune evasion and progression." (PMID 39079960, 2024). "Therefore, we hypothesized that breast cancer cells primarily suppress CD4+ T cells activation through exosomal forms." (PMID 39079960, 2024). "Moreover, KRT14 expression has been implicated in MHC class II presentation in breast cancer, suggesting that down-regulation of KRT14 in TNBC could result in increased MHC II expression and facilitate the activation of CD4+ T cells." (PMID 38566092, 2024). "However, IL-6 receptors IL-6Rα and gp130 were found to be reduced on naïve CD4+ T cells from breast cancer patients compared to healthy donors by flow cytometry, and expression levels correlated with signaling responsiveness to IL-6, identifying a potential mechanism of impaired signaling." (PMID 37741983, 2023). "Moreover, the proportion of CD4+PD-1+T was correlated with the clinicopathology of breast cancer." (PMID 36925914, 2023). "In general, the novel SERGs signature could be applied to screen breast cancer with immunosuppressive microenvironment for the risk score was negatively correlated with ESTIMATE score, tumor-infiltration lymphocytes (such as CD4 + and CD8 + T cell), immune checkpoints and chemotactic factors." (PMID 37596527, 2023). "In this study, circulating CD4+PD-1+T cells were detected with flow cytometry, and it was found that surgical resection of the tumor could reverse the immune exhaustion status of patients with breast cancer." (PMID 36925914, 2023).
breast cancer (continued). "Similarly, by the final cycle of dose-intense chemotherapy among patients with breast cancer, several cell types declined compared to pre-chemotherapy levels, including; B cells, CD4+ T cells, CD8+ T cells and NK cells, and the percentage of activated HLA-DR+ T cells increased." (PMID 37324393, 2023). "On the other hand, B cell activity in patients affected by breast cancer undergoing chemotherapy is typically enhanced and can lead to diverse effects, eliciting either anti-tumor T cell immunity or, conversely, the switch of CD4+ T cells to T-regulatory cells with immunosuppressive effects." (PMID 35568887, 2022). "Additionally, CD4+ T cells were dramatically decreased in the SLN in breast cancer." (PMID 36266717, 2022). "In agreement with this hypothesis, a previous work of our group demonstrated that PODXL expressed on MCF-7 breast cancer cell line accumulates at the immune synapse formed with NK cells and inhibits NK cell activity as well as agonist-induced CD4+ T and CD8+ T cell proliferation." (PMID 35711462, 2022). "In addition, a previous study found that IL25 expression in breast cancer was a positive correlation with infiltrating CD4+T cells and macrophages, whereas IL25 blockade decreased type 2 T cells and macrophages in the primary tumor microenvironments and inhibited lung metastasis." (PMID 35359953, 2022). "Studies have shown that the CD4 + /CD8 + ratio is significantly decreased in patients with some cancers (such as breast cancer, gastric cancer, and lung cancer), HIV, and neuromyelitis optica spectrum disorders, indicating that the immune function of patients may be reduced." (PMID 36225368, 2022). "Similarly, the combination of TNFSF4 (OX40L) fusion protein and poxvirus-based cancer vaccine (MVA-Twist-TRICOM) can also be used effectively to inhibit lung metastasis of breast cancer by increasing the infiltration of CD4+CD8+ T cells and the production of IFN-γ and TNF-α." (PMID 34367975, 2021). "Moreover, flow cytometry and gene expression analysis of CD4+ T cell subsets revealed that highly infiltrated breast cancers also harbor TLS, and express markers such as Cxcl13, ICOS, IFNγ and TBX21/T-bet, commonly associated with follicular T helper (Tfh) and Th1 profiles." (PMID 34122434, 2021). "As previous study has reported that blocking of STAT3 in breast cancer cells induced an antitumor immune response involving CD4+ T cells, which may ameliorate TME via secretion of cytokines, such as TNF-α, IFN-γ, IL-6, and IL-5, as well as chemokines CCL5 and CXCL10." (PMID 33957948, 2021). "Moreover, the presence of CD8+ T-cells has been linked to considerable reductions in the relative risks of death from different subtypes of breast cancer; and in ER-negative cancers, CD4+ and CD8+ T lymphocytes are more closely related to better outcomes than in ER-positive tumors." (PMID 34683171, 2021). "Therefore, we used the TIMER database to analyze the expression levels of RUNX factors and their relationship with the infiltration of six types of immune cells (B cells, CD8+T cells, CD4+T cells, macrophages, neutrophils, and dendritic cells) in breast cancer." (PMID 34485309, 2021). "The presence of macrophages and Th2-polarized CD4+ T cells limits the efficacy of radiotherapy for breast cancer, and eliminating these cells or neutralizing IL-4 may improve the clinical response to cytotoxic therapy in breast cancer patients." (PMID 34625124, 2021). "Based on the presented results, in addition to the prophylactic model, this formulation may hold promise for developing a therapeutic vaccine in the HER2 positive breast cancer in the presence of an appropriate adjuvant and/or CD4 restricted peptides such as PADRE." (PMID 33301467, 2020).
breast cancer (continued). "CD4+ T cells were reported to play a central role in initiating and maintaining anticancer immune responses in human head and neck cancer; meanwhile, they were also reported to correlate with lymph node involvement and unfavorable prognosis in human breast cancers." (PMID 32425694, 2020). "However, NKT, CD8+ T-cells, CD8+ Tcm, CD4+ Tem, cDC cells which may have an anti-tumor effect in breast cancer weren’t enriched in high glycolysis group." (PMID 32070368, 2020). "Thus, we used the TIMER database to evaluate the correlation between FREM1 mRNA expression and six different infiltrating immune cell types (B cells, CD8+ T cells, CD4+ T cells, macrophages, neutrophils and dendritic cells) in different subtypes of breast cancer." (PMID 33031059, 2020). "We found that breast cancer cells upregulate the expression of ICs including PD-1, cytotoxic T lymphocyte-associated antigen-4 (CTLA-4), T cell immunoglobulin and mucin domain-containing protein 3 (TIM-3) and lymphocyte activation gene-3 (LAG-3) in CD4+ T cell subsets." (PMID 31614877, 2019). "However, it remains unclear whether ICOSL-expressed breast cancer cells can directly interact with CD4+ T cells as a mechanism of immune suppression, contributing to the poor OS observed in our study." (PMID 31143539, 2019). "However, interestingly, the ratio of ICOS+ CD4+ T-cells to FoxP3+ CD4+ T-cells significantly increased from 7% pre-vaccination to 23% post-vaccination, which is also accompanied by a three-fold increase in the IFN-γ response in CD4+ T-cells following vaccination to breast cancer patients." (PMID 28304339, 2017). "Thus CCL18 expression by TAMs recruits naive CD4+ T cells to orthotopic breast cancer xenografts." (PMID 28290464, 2017). "Notably, not only the proportion but also total cell numbers of IL-4+CD4+ cells remained in a relatively low level among TILs during the breast cancer development, suggesting that Th2 subset is a subdominant subset compared with the other T cell subsets ( < 4%)." (PMID 25968569, 2015). "Given that our results showed significantly increased CD4+ T cell proportion and numbers in TILs of late stages of breast cancer progression, we reasoned that CD4+ T cell subsets and their roles may alter during breast cancer progression, resulting in tumor promotion rather than tumor surveillance." (PMID 25968569, 2015). "In conclusion, our study implied that upregulation of IDO in breast cancer cells might inhibit local immune surveillance by favoring amplification and infiltration of CD4+CD25+ Tregs in the tumor microenvironment and thus promote metastasis and relate to a bad prognosis." (PMID 22110525, 2011). "In the tumor tissues of breast cancer patients, SIGLEC15 expression was found to be negatively correlated with CD4 and CD8 expression levels." (PMID 41158758, 2026). "Collectively, these results demonstrate that CD4+ T cells and TSLP signaling are required for calcipotriol-induced antitumor response against late-stage breast cancer, which is accompanied by a significant accumulation of IL-24+ cells within the TME." (PMID 39782693, 2025). "Mouse and human breast cancer cells express TSLP, which promotes Th2 differentiation of CD4+ T cells." (PMID 40873585, 2025). "Immunohistochemistry (IHC) analysis further confirmed increased infiltration of CD4+ and CD8+ T cells in RCOR2-KO PyMT mammary tumors compared with wild-type tumors." (PMID 40608411, 2025). "Tregs, identified by their expression of CD4, CD25, and FOXP3, serve as key suppressors of anti-tumor immune responses in the breast cancer TIME." (PMID 41550427, 2025). "Studies, to date, indicate that CD4+ and CD8+ T cells have opposing roles in breast cancer progression and outcomes." (PMID 40141437, 2025). "In summary, TLSs provide a structured setting for the recruitment, activation, and expansion of CD4+ and CD8+ T cells, thereby augmenting anti-tumor immune responses and improving the efficacy of immunotherapy in breast cancer." (PMID 41550427, 2025).
breast cancer (continued). "Further, the mammary tumors from MMTV-RONΔMyeloid mice compared with controls show increased numbers of CD8a+ T cells and CD4+ T cells." (PMID 40282397, 2025). "Mediation analysis revealed that DP (CD4+CD8+) % leukocyte mediated the pathway between gut microbiota (PWY-6263: superpathway of menaquinol-8 biosynthesis II) and breast cancer." (PMID 40248981, 2025). "This is because the functions of CD4+ and CD8+ T lymphocytes in the development of breast cancer are opposed." (PMID 41304988, 2025). "Icariin increases the proportion of tumor-infiltrating CD4+ and CD8+ T cells, reduces the number of MDSCs, and induces their differentiation into macrophages and DCs, restores CD8+ T cell function in 4T1 breast cancer xenograft model in vivo." (PMID 40490812, 2025). "In HER2 + breast cancer, patients with elevated tsMHC-II expression exhibited enhanced CD8 + and CD4 + T cell infiltration and reduced T cell-to-tumor distances, patterns paralleled in tsMHC-I-high tumors." (PMID 40495188, 2025). "Specifically, the authors assessed the status of PD-L1, PD-1, CTLA-4, CD68, CD163, CD11c, iNOS, CD3, CD8, CD4, FOXP3, CD20, and Ki67 along with pan Cytokeratin and CD31 in the TME of 3098 tumors, including 587 cases with breast cancer." (PMID 40243442, 2025). "Subpopulations within the CD4+CD8+, CD4−CD8−, and γδ T cell compartments were analyzed to assess their distribution of luminal A breast cancer patients." (PMID 41301880, 2025). "Ultimately, this activated CD45+CD8+ effector T cells and incapacitated CD4+CD25+Foxp3+ Tregs, transforming “cold” into “hot” tumors and enhancing the anti‐tumor effect of chemotherapeutic agents in breast cancer in vivo." (PMID 39585774, 2025). "For ER+ breast cancer, the selection criteria revealed eight cell types: iCAF, myCAF, cancer luminal A, macrophages, ACKR1+ ECs, differentiated PVLs, CD4+ T cells and CD8+T cells." (PMID 41188599, 2025). "Tertiary Lymphoid Structures (TLSs) facilitate the recruitment and activation of CD4+ and CD8+ T cells in breast cancers, establishing distinct T-cell zones next to B-cell follicles." (PMID 41550427, 2025). "Lacidipine potently augmented the anti‐tumor effects of chemotherapeutic agents on breast cancer in vivo by activating CD45+CD8+ effector T cells and incapacitating CD4+CD25+Foxp3+ Tregs." (PMID 39585774, 2025). "As Icosl depleted, breast cancer didn’t release sIcosl and also significantly enhanced IFNγ expression and inhibited LAG3 presence in both CD4+ and CD8+ T cells." (PMID 40708008, 2025). "In breast cancer, they demonstrated that inflamed tumors (i.e., having high CD8, CD4, FOXP3, and dendritic cell density) along with increased PD-L1 expression on tumor cells and immune cells were associated with prolonged OS." (PMID 40243442, 2025). "Consistently, a similar but moderate enrichment of human ITGB1 expression was also observed in blood DPT cells versus CD4+ and CD8+ T cells, based on scRNA-Seq data of breast cancer patients." (PMID 40955669, 2025). "In breast cancer, CAF-S1 recruits CD4+CD25+ T lymphocytes via CXCL12 secretion, followed by direct contact with T cells through surface molecules OX40L, PD-L2, and JAM2 to prolong their retention." (PMID 40890855, 2025). "Along this line, the amount of CD4(+)PD-1(+) and CD8(+)PD-1(+) is higher in TNBC versus luminal type A breast cancer patients, showing that in TNBC patients, the PD-1/PD-L1 axis is a target for immune checkpoint inhibitors." (PMID 40243442, 2025). "Concurrently, CAFs also recruit CD4+CD25+ T cells to the TME by secreting CCL5, and these T cells stimulate metastatic progression of breast cancer through the RANKL-RANK signaling pathway." (PMID 40890855, 2025). "Studies have shown that an increase in the CD4+/CD8+ ratio correlated with tumour progression and decreased survival in patients with breast cancer." (PMID 40172096, 2025).
breast cancer (continued). "In summary, we demonstrate the efficacy of topical calcipotriol in inhibiting mammary tumor growth in a TSLP- and CD4+ T cell–dependent manner." (PMID 39782693, 2025). "In this study, breast cancer patients had significantly reduced levels of CD3 + T cells, CD4 + T cells, CD4 + /CD8 + ratio, and NK cells, confirming that the transition of a tumor from benign to malignant can lead to significant immunosuppression." (PMID 38834662, 2024). "According to the correlation between telomerase gene expression and immune infiltration, it has been found that there is a higher proportion of CD4+ T cells, CD8+ T cells and macrophage infiltration in breast cancer patients." (PMID 39669558, 2024). "In breast cancer patients, TGF-β produced by CAFs or M2 macrophages promoted the differentiation of CD4+ T cells into Tregs (FOXP3+ CD4+)." (PMID 39596815, 2024). "A previous study reported that naive CD4 + T cells were recruited and transformed into regulatory T cells (TREGs) by macrophage-derived CCL18 in breast cancer." (PMID 39816386, 2024). "CIRP overexpression also decreased CD4+ helper T cells and increased CD8+ cytotoxic T cells in mammary tumors." (PMID 38397942, 2024). "The IFN-γ levels dropped significantly 72 h after culturing the breast cancer cells in the CM of the CD3+, CD4+ and CD8+ T lymphocytes." (PMID 39262976, 2024). "Future studies cananalyze the composition of CD4+T and CD8+T cells internal lymphocytes in patients with breast cancer." (PMID 38263363, 2024). "The analytical results demonstrated that breast cancer patients showed significantly lower levels of CD3 + T cells, CD4 + T cells, CD4 + /CD8 + ratio, NK cells, and LMR compared to benign breast tumor women (P < 0.05)." (PMID 38834662, 2024). "In contrast, levels of inter-patient heterogeneity, often even within the same breast cancer subtype, were evident for a variety of cells including macrophages, memory B-cells, naïve B-cells, iCAFs, NK cells, NKT cells, CD4 + T-cells, and CD8 + T-cells." (PMID 39529126, 2024). "For mice implanted with 4T1 mammary tumor cells, significantly increased percentages and absolute numbers of CD3+T cells, CD4+T cells, and CD8+T cells were observed in the MWA + 2DG and MWA + PBS groups compared to the 2DG and PBS groups." (PMID 38821965, 2024). "For patients with breast cancer, although CD4+ T cells counts are equal or even higher than those healthy individuals, the CD3+ T cells and CD4+ T cells gradually decrease with the lymphatic metastases." (PMID 38826094, 2024). "Our results confirmed that ASC-exos promoted the TOX, CD4, and LYZ1 expression and inhibited the Mettl7b and Serpinb2 expression in breast cancer tumors, which were significantly enriched in the Human T-cell leukemia virus 1 infection pathway." (PMID 38294569, 2024). "The levels of CD3+T cells, CD4+T cells, CD8+T cells, CD4+/CD8+ ratio, NK cells, CD3+CD4−CD8−T cells, and LMR were found to be related to the occurrence of breast cancer when analyzing data from patients with benign and malignant breast diseases." (PMID 38263363, 2024). "Given that CD4 + CD25 + Foxp3 + is the predominant Treg phenotype, we utilized hospital cohort breast cancer samples for IHC testing of CCL11, CD4, and Foxp3 proteins." (PMID 38305920, 2024). "Compared with primary breast cancer, breast cancer brain metastasis was short of CD8+ T cells and CD4+ T cells, while the macrophages and monocytes were higher than those in primary breast cancer." (PMID 39157383, 2024). "We also demonstrated a higher abundance of Ki67 expressing CD4+ T lymphocytes and CD8+ T lymphocytes in TN breast cancer." (PMID 38711512, 2024). "The number of CD3+CD4+ and CD3+CD8+ cells in breast cancer tissue was significantly enhanced, indicating a robust antitumor immune response." (PMID 39045563, 2024). "In breast cancer, we have shown that higher levels of CD8+ T cell infiltration and increased CD4+ activity are correlated with a better patient prognosis." (PMID 38398074, 2024).